TK1 (thymidine kinase 1)
Diseases named in the same sentence as TK1 in open-access papers (continued):
Sharing a sentence is not in itself a finding about the gene and the disease.
tumor (continued). "In order to demonstrate that TK1 upregulation is an early event in tumor tissue formation, tissue arrays were obtained and stained for TK1 by immunohistochemistry." (PMID 22778736, 2012). "At Day 5 expression of TK1 was decreased in the SW620 tumor control group compared to baseline (-27±6%; P = 0.02)." (PMID 23226334, 2012). "The imaging data were compared with Ki67 and TK1 gene expression and tumor growth measured with computed tomography (CT)." (PMID 23226334, 2012). "Further research would be required to establish if these TK1 positive cells are in fact a result of the tumor tissue." (PMID 22778736, 2012). "It is known that normal, non-malignant cells die in G1/G0 of the cell cycle, where the intracellular concentration of TK1 is low, while tumour cells die also in S/G2 stage of the cell cycle, where TK1 concentration is high, generating more TK1 in serum." (PMID 22247653, 2011). "Serum TK1 activity has been used to monitor the extent of tumour metastasis and prognosis in patients with acute leukaemia, chronic leukaemia, Hodgkin's and non-Hodgkin's lymphoma, bladder carcinoma, and cervical carcinoma." (PMID 19396699, 2009). "The cell cycle regulation makes TK1 a highly interesting marker for cell proliferation and as a marker for tumour growth." (PMID 19396699, 2009). "Furthermore, pan‐cancer analyses have shown that TK1 facilitates tumor progression by promoting Th2 cell polarization, which contributes to an immunosuppressive microenvironment." (PMID 41584726, 2026). "Despite description as a marker for occult neoplastic diseases, TK1 is not diagnostic for malignant nasal tumors in dogs." (PMID 40260215, 2025). "In addition, while differences in tumor biomarkers (TK-1, LDH, β2M) were observed between groups, formal correlation analyses between biomarker changes and objective clinical responses (such as lymph node size reduction) were not performed." (PMID 40520425, 2025). "Moreover, circulating tumor DNA (ctDNA), circulating tumor cells (CTCs) and serum thymidine kinase-1 activity are under investigation as liquid biopsy-based biomarkers, offering minimally invasive options for real-time monitoring." (PMID 40940886, 2025). "KEGG pathway analysis and GO analysis of the differentially expressed genes demonstrated that TK1 knockdown can affect the biological functions of PCa cells, including cell adhesion, cellular senescence, and cell junctions, which are critical for tumor progression." (PMID 39803822, 2025). "They concluded that TK1 could be a valuable tumour marker for diagnosing and stratifying prostate cancer." (PMID 40830177, 2025). "Furthermore, expression data from the TCGA database showed that TK1 mRNA levels were significantly increased with advancing tumor stage and lymph node metastasis status in HNSC patients." (PMID 40564887, 2025). "Similarly, studies in breast and esophageal squamous cancer have shown that high serum or tissue levels of TK1 correlate with tumor progression and reduced survival." (PMID 40564887, 2025). "This elevation suggests that TK1 might contribute to the increased DNA synthesis and replication required for rapid tumour cell proliferation." (PMID 40699738, 2025). "Moreover, tumor biomarkers such as TK-1, LDH, IFN-γ, and β2M showed trends that favor the test group, indicating potential immunomodulatory and tumor-suppressive effects." (PMID 40520425, 2025). "Also, it highlights TK1’s potential in discriminating between moderately aggressive and highly aggressive tumours, which is crucial for tailoring therapeutic approaches." (PMID 40830177, 2025). "Here, the tumor-associated antigens in THCA were identified via a comprehensive analysis of somatic mutations and amplified genes, which revealed that TK1 could serve as a potent antigen target of THCA." (PMID 39403328, 2024). "TK1 was considered as a candidate agent for tumor prognosis." (PMID 39403328, 2024).
tumor (continued). "The TK1 enzyme is a valuable tumor biomarker as it reflects the rate of cellular proliferation." (PMID 39006942, 2024). "Thymidine kinase 1 (TK1) is highly expressed in the cytosol of proliferating tumor cells." (PMID 39726703, 2024). "TK1, which is associated with CD8+ T cells, is a marker of abnormal tumor cell proliferation." (PMID 38748299, 2024). "Thus, TK1 IHC determines the number and intensity of stained cells showing the cell proliferation rate, including normal cells and tumour cells, which is important to know when trying to assess a true cell proliferation rate." (PMID 36969497, 2023). "TK1 is associated with aggressive tumor features such as advanced stage, high grade, ER/PgR negative, tumor necrosis, and vascular invasion, suggesting its central role as a BC proliferation marker." (PMID 37767092, 2023). "TK1 was expressed at low levels in KICH but highly expressed in 13 other tumor types." (PMID 37854594, 2023). "However, TK1 activity remains elevated in the G2 and M phases in highly proliferating cells, such as in tumor cells." (PMID 37808109, 2023). "RABL6 and TK1 are well-known oncogenes and promote tumor proliferation in many types of cancers." (PMID 36806253, 2023). "Additionally, our work revealed the underestimable potential of TK1 as a tumor biomarker and immunotherapeutic target." (PMID 37767092, 2023). "To test the potential use of the anti-TK1-sdAb antibodies for the immunotargeting of cancer cells that express mTK1, we co-cultured tumor cells expressing high levels of TK1 with human MNCs, added anti-TK1-sdAb-Fc antibodies and monitored the ADCC response over time." (PMID 35239730, 2022). "The antibody fragments isolated here may represent a valuable resource for the detection and the targeting of TK1 on tumor cells." (PMID 35239730, 2022). "Furthermore, xenograft model assay suggested that knockdown TK1 in PC-3 cells significantly inhibited tumor growth compared with scramble cells." (PMID 35559045, 2022). "Previously studies have reported that TK1 took a key role in tumor initiation and progression." (PMID 35559045, 2022). "Next, the correlation between tumor immune infiltration and TK1 expression was analyzed." (PMID 35559045, 2022). "Additionally, TISIDB was applied to explore the correlation between TK1 expression and tumor-infiltrating lymphocytes, immune subtypes, and immune regulatory factors." (PMID 35559045, 2022). "In addition, transwell assay further revealed the potential stimulative role of TK1 on tumor cell mobility in C42 and PC-3 cells." (PMID 35559045, 2022). "We hypothesize that engineered single domain antibodies (sdAb) specific for TK1 can efficiently target tumor cells expressing high levels of TK1." (PMID 35239730, 2022). "The hypermethylation status of TK1 may contribute to the inhibition of tumor progression in PCa, which helps explain the hypomethylation status of TK1 in PCa." (PMID 36035114, 2022). "They revealed that the highly expressed TK1 and PCDGF levels were associated with the heavy release of TK1 from cancer tissue cells into the peripheral circulation and the regulatory role of PCDGF in tumor immunity." (PMID 35368891, 2022). "The expression of TK1 increased with the increase of tumor Gleason score (p < 0.001)." (PMID 35559045, 2022). "TK1 is involved in the tumor immune response and may therefore be a potential target for immunotherapy of HCC." (PMID 35127491, 2021). "Here, it is shown that differential response of the serum concentration of thymidine kinase 1, an enzyme involved in the DNA synthesis and released from the tumor into the blood, 48 h after the first cycle of NAC, predicts long-term outcome in localized advanced ER+/HER2-BC." (PMID 34771604, 2021). "Our hypothesis is that TK1 is a more sensitive tumor cell turnover marker compared with lactate dehydrogenase (LD), commonly used as a biomarker in lymphoma." (PMID 34471484, 2021).
tumor (continued). "Interestingly, at the stage 1–2 AK4 gene signature interface, the pyrimidine salvage protein thymidine kinase 1 (TK1) was predicted to be amongst the most influential for LUAD tumor progression from stage 1 to stage 2." (PMID 34940617, 2021). "Moreover, loss of TK1 results in a loss of GDF15, one of the TGF-beta ligands, leading to reduced tumor activity and metastasization." (PMID 34830698, 2021). "Furthermore, TK1 expression was significantly related to pathological stage, tumor stage and lymph node metastasis, with high TK1 expression being an unfavorable prognostic factor for HCC." (PMID 35127491, 2021). "In summary, high TK1 expression is associated with poor prognosis in HCC patients and may promote the development of this cancer type by inhibiting the apoptosis of tumor cells and promoting their proliferation." (PMID 35127491, 2021). "Furthermore, in our subsequent study, we found that IGF2BP2 and TK1 have significantly correlated expression in tumor cells, and our bioinformatics analysis data unraveled that TH1 expression was abnormally elevated in ESCC." (PMID 34386421, 2021). "The expression of TK1 mRNA in HCC tumor tissues was significantly higher than in normal tissues." (PMID 35127491, 2021). "In addition, they found that increased levels of TK1 and C-reactive protein also correlated with increasing grades of tumors, and both of these markers when used to evaluate tumor presence and grade correlated with the standard Neoplastic Index." (PMID 33292474, 2020). "“However, even with abundant evidence for the overexpression of TK1 (protein) in a wide variety of cancer and the association of this protein with poor prognosis, no study thus far has analyzed the functional implication of TK1 inhibition on tumor growth and progression”." (PMID 33292474, 2020). "The targeting of TK1 in malignant cells using monoclonal antibodies may be a feasible approach for the elimination of high TK1 expressing tumor cells." (PMID 32317865, 2020). "Therefore, the DNA incorporation rate of 11C-4DST in tumor cells is affected by the activity of TK1." (PMID 34191155, 2020). "Therefore, TK1 can be used as a marker to reflect the growth and proliferation degree of tumor cells." (PMID 32202305, 2020). "The exploration of TK1 as a tumor target may lead to the development of other TK1-based immunotherapeutics." (PMID 32317865, 2020). "Therefore, it seems likely to be a different pathway for tumour cell elimination, namely the necrotic pathway, and this would be responsible for the release of TK1 into blood." (PMID 32423477, 2020). "Additionally, TK1 was within the “DNA replication” set that was highly expressed and involved in PCa tumor proliferation." (PMID 33292474, 2020). "An explanation for this could be that during treatment cell loss in normal tissues temporarily exceeds the capacity of the apoptotic pathway, resulting in a non-tumour specific release of TK1 into blood." (PMID 32423477, 2020). "Furthermore, TK1 has been reported as a tumor biomarker and it also exhibits potential in drug discovery and as a therapeutic target." (PMID 32650368, 2020). "Therefore, our data demonstrating that reduced Rho GTPase activity that results from knockdown of TK1 can block LUAD tumor growth and metastasis are consistent with the published literature." (PMID 31589613, 2019). "Collectively, our data identify TK1 as a key regulator of LUAD tumor growth and metastasis, and suggest that this protein may be utilized both as a predictive biomarker for poor prognosis in LUAD and as a target for LUAD therapy." (PMID 31589613, 2019). "However, even with abundant evidence for the overexpression of TK1 in a wide variety of cancer and the association of this protein with poor prognosis, no study thus far has analyzed the functional implication of TK1 inhibition on tumor growth and progression." (PMID 31589613, 2019). "TK1 expression and tumor thymidine concentrations were profoundly reduced." (PMID 29794225, 2018).
tumor (continued). "Boron-containing purines, pyrimidines, thymidines, nucleosides and nucleotides also have been investigated as BNCT delivery agents, in particular 3-carboranyl thymidine analogues (3CTAs), which specifically target thymidine kinase-1 (TK1)-expressing tumor cells." (PMID 29914561, 2018). "This suggests that TK1 activity levels may increase through disease progression and endocrine resistance, as a consequence of uncontrolled tumor proliferation." (PMID 29662653, 2018). "We found that TNBC tumor samples expressed higher levels of TK1 than HER2+ tumor samples." (PMID 30214377, 2018). "We hypothesized that plasma TK1 activity may be a “bona-fide”, non-invasive circulating marker of tumor proliferation in patients with MBC." (PMID 29662653, 2018). "The use of Paclitaxel on a chemotherapeutic regimen has been shown to have minimal effect on [18F]FLT uptake, since it induces cell cycle arrest in an advanced point which doesn’t affect TK1 expression or change cell proliferation, even though it reduces tumor growth." (PMID 29791503, 2018). "In keeping with the well established prognostic role of tumor proliferation in HR+ BC, we hypothesized that low baseline levels of TK1 might identify a sub-group of patients with HR+ MBC with extended clinical benefit while on ET." (PMID 29662653, 2018). "CC531 tumor sections were analyzed for necrosis, Ki67, TK1, and ENT1 expression." (PMID 27798786, 2017). "Additionally, TK1 was only detectable in the tumor lysates, with two of these showing high expression levels, and only minimal expression in the remaining lysates." (PMID 28289079, 2017). "This is in spite of the statistically significant reduction in tumor TK1 mRNA at C1D1." (PMID 29162134, 2017). "Therefore, studies including patients with advanced disease in which tumor cells contribute to the majority of the serum TK1 activity are warranted." (PMID 29162134, 2017). "Similarly, our previous studies in the TRAMP model demonstrated that an increase in DNA damage and TK1 expression was observed only in the single case where tumor growth escaped the suppressive effect of folate depletion." (PMID 29262598, 2017). "A reduction in serum TK1 activity by palbociclib had a sensitivity of 94.1% (32 of 34, 95% CI 86.2% -100%) and a specificity of 84% (21 of 25, 95% CI 69.6% -98.4%) in predicting tumor Ki-67 response in this patient population." (PMID 29162134, 2017). "However, it does not incorporate into the DNA chains and remains trapped after phosphorylation by thymidine kinase-1 (TK-1), which is increased at the S-phase of the cell cycle, reflecting, in this context, tumor proliferation." (PMID 28612247, 2017). "The tracer 3′-deoxy-3′-[18F]-fluorothymidine ([18F]FLT) has often been used for tumor imaging over the last years since it is a substrate of thymidine kinase-1 (TK1) that is overexpressed in proliferating cells during the late G1 and S phases of the cell cycle when the cell synthesizes DNA." (PMID 27070087, 2016). "This study also underlines the need for a more detailed investigation of the determinants of thymidine metabolism, such as the expression and activity of the enzymes TK1, thymidine phosphorylase and thymidylate synthase, in a similarly wide range of tumour models." (PMID 27515446, 2016). "Thus, there are different ratios of active and inactive TK1 in sera from dogs with different types of tumor disease as demonstrated in this study." (PMID 26366881, 2015). "In addition, several investigators have shown that patients with high TK1 expression have a relatively poor prognosis with some tumor types." (PMID 25901475, 2015). "TK1 and TS are highly upregulated in various tumor tissues and may serve as potential targets for cancer therapy." (PMID 25901475, 2015). "Thus far, no studies have been conducted where the specific activities of STK1 or the molecular forms of TK1 in different types of tumor diseases have been analyzed in detail." (PMID 25881026, 2015).
tumor (continued). "However, a lack of more detailed information about the molecular forms of sTK1 in dogs with tumor disease is a problem when it comes to using TK1 as a biomarker." (PMID 25293656, 2014). "In our last published study we demonstrated the molecular forms of STK1 in an ALL patient and it was hence highly interesting to repeat these studies together with a characterization of the molecular forms of cellular (i.e. the tumor cells) TK1 from the same ALL patient." (PMID 25293656, 2014). "TK1 expression was, subsequently, also found in nuclei of different types of tumor tissues." (PMID 23693054, 2013). "Inactivation of TK1 may be the result of tumor cell death leading to denaturation/inactivation of the enzyme." (PMID 24649267, 2013). "The aim of this study was to determine if TK1 upregulation is an early event in tumor development." (PMID 22778736, 2012). "Similar trends have been found between tumor tissue and TK1 expression levels." (PMID 22778736, 2012). "Tumor TK1 levels, similar to serum TK1 levels, also correlate with both stage and grade." (PMID 22778736, 2012). "As [18F]FLT uptake is primarily mediated by TK-1 activity, it can be argued that k3 may be a more accurate predictor of tumour proliferation than Ki, which is also dependent on other factors (i.e., blood flow)." (PMID 22392642, 2012). "This study seeks to determine whether, similarly to serum TK1, tumor TK1 upregulation is an early event in tumor development and may aid in the identification of precancerous tissue." (PMID 22778736, 2012). "As thymidine kinase 1 (tk1) shows an S-phase dependant expression, the intracellular accumulation of labeled nucleosides that are substrates for TK1 reflects DNA synthesis and thus tumor proliferation." (PMID 21603240, 2011). "Hence, TK1 in serum is useful in health screening as a reliable tumour-proliferating marker alone or in combination with routine inspections for an early risk warning assessment of malignant process." (PMID 22247653, 2011). "However, the development by us of new generations of chicken polyclonal (IgY) and mouse monoclonal anti-TK1 antibodies extended the clinical use of TK1 to almost all types of solid human tumours, for both serum and immunohistology analysis." (PMID 22247653, 2011). "Imaging results were validated by tumor volume changes and gene-expression of Ki67 and TK1." (PMID 20885974, 2010). "This makes TK1 an interesting marker for cell proliferation and tumour growth." (PMID 19396699, 2009). "The role of TK1 in tumour growth has led to the use of TK1 as a cancer serum marker." (PMID 19396699, 2009). "The reduction in TK-1 levels over time suggests that rcIL-15 may contribute to tumor suppression." (PMID 40520425, 2025). "To analyze the mechanism by which TK1 promotes PCa proliferation, migration, and invasion, we performed transcriptome sequencing and found that TK1 regulates cell adhesion, cellular senescence, and cell junctions, which are critical for tumor proliferation, migration, and invasion." (PMID 39803822, 2025). "In‐depth studies have shown that CDK1 regulates tumor cell cycle control, and TK1, a rate‐limiting enzyme for DNA repair synthesis, is a known S‐phase‐dependent enzyme of the cell cycle and has been widely used as a serum marker for tumor cell proliferation dynamics." (PMID 39949984, 2025). "Elevated exocytosis, in combination with the upregulated TK1 in tumor cells, may point to the higher enzyme activity we observe in the malignant cell lines used in this study, compared to the prostasomes from healthy males or EV from the regular epithelial cell line." (PMID 39006942, 2024). "It has been shown that increased TK1 mRNA levels in the plasma-derived sEVs are also associated with clinical resistance to CDK4/6 inhibitors in metastatic breast cancer patients, which agrees with our data, and strengthen the plausibility of TK1 as a reliable tool for determining tumor progression." (PMID 39006942, 2024).